MPO (myeloperoxidase)
Diseases named in the same sentence as MPO in open-access papers (continued):
Sharing a sentence is not in itself a finding about the gene and the disease.
diabetes (continued). "In the other models wherein diabetes, HDL-C, Ca, or P was a variable instead of LDL-C, MPO-AAV, dialysis dependence, and hypertension were similarly significant factors." (PMID 33481903, 2021). "Using the blood plasma of type 2 diabetes mellitus (T2DM) patients, we performed a parallel analysis of the two most studied PMN enzymes: myeloperoxidase (MPO) and elastase (EL)." (PMID 32908806, 2020). "In this study, the role of MPO and ANGPTL6 on diabetes and obesity was assessed, and results showed that although both markers are elevated in obese participants, diabetes status can affect their physiological function." (PMID 32277104, 2020). "ARC: age-related cataract; HT: hypertension; DM: diabetes mellitus; XO: xanthine oxidase; MPO: myeloperoxidase; LLF: lipofuscin-like fluorophores; MDA: malondialdehyde; SH: thiol; FRAP: ferric reducing/antioxidant power assay; GPx: glutathione peroxidase; SOD: superoxide dismutase." (PMID 29590254, 2018). "Chronic inflammation occurred in the diabetic pancreas accompanied by up-regulation of CCAAT/enhancer-binding protein beta (C/EBPβ) and its targets (TNFα, Il6, CRP, and Fn1) as well as myeloperoxidase (Mpo) and C-X-C chemokine receptor type 2 (Cxcr2)." (PMID 26110898, 2015). "Thus, decreased MPO activity in patients with poorly controlled diabetes may be due to hyperglycemia-associated negative modulation of the enzymatic activity." (PMID 26719776, 2015). "Diabetes mellitus significantly modified this relationship (p-interaction = 0.028), with diabetic individuals showing amplified risks at higher plasma MPO (Q5 OR = 1.84 vs. non-diabetic Q5 OR = 1.15)." (PMID 40401059, 2025). "Before HDF treatment, patients with diabetes exhibited significantly lower levels of NETosis markers than those without diabetes, including MPO (P = 0.03, n = 9), H3 (P = 0.02, n = 9), and NE (P = 0.03, n = 9)." (PMID 40980683, 2025). "This is not surprisingsince diabetes is known to promote a systemic pro-inflammatory state.Furthermore, MPO was shown to be predictive of insulin resistance in a populationof obese patients." (PMID 39077419, 2023). "This outcome was verified after controlling for established demographic, clinical and laboratory factors and biomarkers of HF survival, including N-terminal pro b-type natriuretic peptide, HSP, MPO, CRP, creatinine, history of diabetes and more, in all three groups of patients." (PMID 37512127, 2023). "Serum MPO levels and activities were measured in 161 patients with diabetes with plaque progression (plaque progression group) and 87 patients with diabetes with no plaque progression (no plaque progression group)." (PMID 36404308, 2022). "The activity of the prooxidative enzyme myeloperoxidase in the gingival crevicular fluid of periodontal patients with diabetes is reduced compared to non-diabetics and non-periodontal patients with diabetes." (PMID 32431669, 2020). "But, other risk factors such as gender, smoking or addiction, hyperlipidemia and diabetes, did not influence blood levels of IL-18, MPO and MMP-9." (PMID 31516856, 2019). "Cardiac MDA level, TOC and MPO activity were significantly increased and TAC was significantly decreased in hearts of diabetic rats, indicating the potent oxidative action of diabetes on cardiac tissues." (PMID 29959408, 2018). "Patients with diabetes and periodontal disease have a lower activity of the prooxidative enzyme myeloperoxidase in the gingival crevicular fluid, compared to nondiabetics." (PMID 25525432, 2014). "FF treatment successfully prevented the diabetes-induced increase in aortic MPO levels; however it failed to affect the increased serum TNF-α levels." (PMID 21234421, 2010). "MPO levels also increased as a function of age in patients without diabetes, R = 0.44." (PMID 36463116, 2022).
diabetes (continued). "The activity of the prooxidative enzyme myeloperoxidase in the gingival crevicular fluid of periodontal patients with diabetes is low compared to that of patients without diabetes and patients with diabetes but without inflammatory damage of the periodontal tissue." (PMID 35330341, 2022). "Serum MPO levels are increased in patients with diabetes compared with patients without diabetes." (PMID 36404308, 2022). "Moreover, serum levels of MPO are elevated in patients with diabetes compared with patients without diabetes." (PMID 36404308, 2022). "In addition, serum MPO levels are higher in patients with diabetes than in patients without diabetes." (PMID 36404308, 2022). "Taken together, our findings suggest that both MPO and ANGPTL6 may regulate obesity, although MPO exerts this effect independent of diabetes while ANGPTL6 may have a modulatory role in diabetes." (PMID 32277104, 2020). "The present data showed that MPO levels are elevated in obesity irrespective of diabetes status." (PMID 32277104, 2020). "However, the role of both ANGPTL6 and MPO in both obesity and diabetes in humans has not been determined." (PMID 32277104, 2020). "Therefore, contrary to our hypothesis, the effect of MPO was not mediated by LBP similar to a Japanese study among diabetes patients which reported LBP was not different among patients with or without bacteraemia." (PMID 40608790, 2025). "After switching to HFHD, patients with diabetes continued to exhibit significantly lower NETosis markers than those without diabetes following HFHD treatment, including MPO (P = 0.03, n = 10) and H3 (P = 0.03, n = 9)." (PMID 40980683, 2025). "In metabolic disorders like diabetes, melatonin demonstrates its antioxidant capabilities by normalizing malondialdehyde (MDA) and myeloperoxidase (MPO) levels while reducing cleaved caspase-3 expression, which signals its role in mitigating cellular damage." (PMID 39703668, 2024). "Patients without diabetes showed a significant increase in the following markers: dsDNA (P = 0.04, n = 10), H3 (P = 0.02, n = 10), and NE (P = 0.03, n = 9); whereas PAD4 (P = 0.07, n = 10) and MPO (P = 0.9, n = 10), were not statistically different." (PMID 40980683, 2025). "In patients with diabetes, the following NETosis markers were significantly increased after HFHD treatment compared with HDF; dsDNA (P = 0.03, n = 9), PAD4 (P = 0.04, n = 10), and NE (P = 0.03, n = 10); whereas H3 (P = 0.6, n = 10) and MPO (P = 0.2, n = 10,) markers were not significantly different." (PMID 40980683, 2025).
ANCA-associated vasculitis (109 papers, 2008 to 2026). "Myeloperoxidase (MPO)-specific antineutrophil cytoplasmic antibody (ANCA)-associated vasculitis (AAV) can present with diffuse alveolar hemorrhage (DAH), a life-threatening pulmonary complication, even in the absence of renal involvement." (PMID 42158806, 2026). "Antineutrophil cytoplasmic antibodies targeting MPO or PR3 are a hallmark of the subgroup of small-vessel systemic vasculitis called ANCA-associated vasculitis (AAV)." (PMID 40520655, 2025). "For patients with MPO-ANCA-associated vasculitis, the induction-remission rates of rituximab-based regimens and those based on cyclophosphamide are comparable." (PMID 40308572, 2025). "The association between high NLR and anti-MPO levels suggests that systemic neutrophilia is linked to autoantibody production, mirroring the relationship seen in ANCA-associated vasculitis and indicating a common pathway of neutrophil-derived immunopathology." (PMID 41239211, 2025). "Previous case reports reveal that most patients with drug-induced ANCA-associated vasculitis have MPO-ANCA, frequently in very high titers, as found in our patient." (PMID 40443627, 2025). "Positive myeloperoxidase and perinuclear antineutrophil cytoplasmic antibody titers confirmed the diagnosis of antineutrophil cytoplasmic antibody-associated vasculitis (AAV)." (PMID 40777707, 2025). "ANCA-associated vasculitis is an autoimmune disease in which circulating anti-neutrophil cytoplasmic antibodies (ANCAs) are directed against MPO or PR3, directly activating primed neutrophils via FcγR and complement receptor engagement." (PMID 41335221, 2025). "This case report highlights the successful diagnosis and management of a 66-year-old male with MPO-associated renal-limited vasculitis, a rare form of ANCA-associated vasculitis (AAV) affecting only the kidneys." (PMID 40636326, 2025). "Following hemodialysis and infection-related complications, treatment with rituximab was initiated to suppress the progression of MPO-ANCA-associated vasculitis." (PMID 41209892, 2025). "In experimental murine myeloperoxidase (MPO)-ANCA-associated vasculitis (AAV), MC-derived IL-10 enhanced the immunosuppressive function of Treg and played a protective role in MPO-related inflammation." (PMID 39355120, 2024). "Development of ANCA in ANCA-associated vasculitis is linked with the loss of immunological T-cell and B-cell tolerance to one of two neutrophil proteins: leukocyte proteinase 3 or myeloperoxidase." (PMID 39575034, 2024). "Based on our study’s results, decreased ceruloplasmin levels appear to be a marker of poor prognosis in anti-MPO ANCA-associated vasculitis." (PMID 39388433, 2024). "The association between MPO-ANCA-associated vasculitis (AAV) and interstitial lung disease (ILD) has been well established." (PMID 38445024, 2024). "In ANCA-associated vasculitis, MPO is primarily expressed on the surface of activated neutrophils, where anti-MPO antibodies bind to it, triggering the release of reactive oxygen species." (PMID 39388433, 2024). "The HLA-DQ locus is shared with MPO-ANCA-positive EGPA and MPO-ANCA-positive ANCA-associated vasculitis (AAV)." (PMID 37762936, 2023). "If pyrexia, prolonged general malaise, urinary occult blood, or renal impairment is observed, the onset of MPO-ANCA-associated vasculitis should be considered." (PMID 37101523, 2023). "Of these, 5/6 patients investigated were found to be positive for either p-ANCA or MPO and were re-diagnosed with concomitant ANCA-associated vasculitis to the SLE diagnosis." (PMID 37439924, 2023). "Levels of MPO+EVs and activity assay variables in ANCA-associated vasculitis (AAV) patients and controls." (PMID 37915326, 2023). "In patients with ANCA-associated vasculitis in primary SS course, most cases present anti-MPO specificity." (PMID 37569455, 2023).
ANCA-associated vasculitis (continued). "In the literature, eight cases were new-onset ANCA-associated vasculitis, five cases were associated with myeloperoxidase (MPO), and three cases with proteinase 3 (PR3)." (PMID 35632497, 2022). "Increased MPO–DNA complex in serum has been found in many autoimmune diseases such as rheumatoid arthritis, Behcet’s disease, and ANCA-associated vasculitis." (PMID 35774788, 2022). "Autoreactivity to myeloperoxidase (MPO) can also lead to antineutrophil cytoplasmic antibody (ANCA)-associated vasculitis (AAV)." (PMID 35878202, 2022). "This was in line with previously reported beneficial effects of anti-ApoA2, such as effective recovery from renal disorders and decreased levels of MPO-ANCA and inflammatory cytokines in SCG/Kj mice models of MPO-ANCA-associated vasculitis (MAAV)." (PMID 36550471, 2022). "A previous article reported an interesting case of acute MI without evidence of typical advanced atherosclerotic lesions, including necrotic core, in a patient with MPO-ANCA-associated vasculitis." (PMID 35741296, 2022). "The first description of macrophage extracellular traps (METs) in autoimmune disease was the observation of (METs) within the kidney glomeruli of patients with MPO-ANCA-associated vasculitis." (PMID 35409152, 2022). "The presence of ANCA against myeloperoxidase (MPO) and proteinase 3, two proteins in neutrophil granules, is characteristic of ANCA-associated vasculitis." (PMID 35409152, 2022). "Our research group had also demonstrated that MetS was associated with poor health outcomes including ACS in patients with MPO-ANCA-associated vasculitis." (PMID 35741296, 2022). "The prevalence of DAH was comparable between the groups of PR3-AAV and MPO-AAV in the Rituximab in ANCA-associated Vasculitis (RAVE) trial." (PMID 34760903, 2021). "In a similar model of PTU-induced MPO-ANCA associated vasculitis, BALB/c mice were given PTU; NET formation was attenuated by peptidylarginine deiminase (PAD) inhibition, with lower MPO-ANCA titres." (PMID 32373109, 2020). "Among type III Cr.GN, ANCA associated vasculitis (AAV) was seen only in 50% patients (anti-MPO 24%; anti-PR3 26.3%)." (PMID 32766459, 2020). "MPO contributes to oxidative damage involved in the pathogenesis of ANCA-associated vasculitis, suggesting therapeutic utility in MPO inhibition." (PMID 33023023, 2020). "Several lines of evidence indicate that anti-neutrophil cytoplasmic antibodies (ANCAs), especially myeloperoxidase (MPO)-ANCAs, are pathogenic auto-antibodies in ANCAs-associated vasculitis (AAV)." (PMID 31455233, 2019). "Although the illness improved after cessation of hydralazine, MPO-ANCA-associated vasculitis relapsed 16 months later." (PMID 29929470, 2018). "Neutrophil extracellular traps (NETs) are extracellular web-like DNA structures containing antimicrobial proteins such as MPO, which have recently been implicated in the pathogenesis of ANCA-associated vasculitis." (PMID 28878769, 2017). "In this study, we attempted to establish novel mouse models of MPO-ANCA-associated vasculitis according to the protocol for the rat model." (PMID 27375623, 2016). "Although further studies are needed to clarify their safety and effectiveness, PAD inhibitors are potential candidates as novel therapeutic agents for various NET-related diseases, including MPO-ANCA-associated vasculitis." (PMID 27375623, 2016). "For this purpose, we attempted to generate novel mouse models of MPO-ANCA-associated vasculitis according to our previous protocol utilized for establishment of a rat model of this disease." (PMID 27375623, 2016). "Renal biopsy revealed crescentic glomerulonephritis (GN) pauci-immune type, suggestive of MPO-ANCA-associated vasculitis (MPO-AAV)." (PMID 27891268, 2016). "We treated five strains of mouse with PMA and PTU corresponding to the previously established protocol for the rat model of MPO-ANCA-associated vasculitis." (PMID 27375623, 2016).
ANCA-associated vasculitis (continued). "Higher levels of serum IL-17A, IL-23, MPO and Pr3-specific Th17 cells are present in subjects with ANCA-associated vasculitis." (PMID 25964886, 2015). "In conclusion, plasma CFH levels are associated with disease activity, and, to some extent, associated with composite outcomes of patients with MPO-ANCA-associated vasculitis." (PMID 25994214, 2015). "Among these, the prevalence of HLA-DPB1*0401 allele was higher in patients with PR3-ANCA associated vasculitis than in patients with MPO-ANCA associated vasculitis or healthy controls." (PMID 26223225, 2015). "The Japanese patients with MPO-ANCA-associated vasculitis (JMAAV) trial revealed the usefulness of severity-based treatment, in which low dose corticosteroid and, if necessary, cyclophosphamide or azathioprine were recommended in patients with mild form." (PMID 25949841, 2015). "Our previous studies found that in PTU-induced AAV, the most important target antigen of ANCA is MPO, and the immunologic characteristics of MPO-ANCA are associated with the development of PTU-induced ANCA-associated vasculitis." (PMID 24252385, 2013). "In 143 patients with MPO-ANCA-associated vasculitis admitted to Kyorin University Hospital from 1989−2010, 29 cases relapsed (relapse rate 20 %)." (PMID 23504409, 2013). "The current study investigated linear epitopes of MPO in patients with PTU-induced ANCA-associated vasculitis." (PMID 24252385, 2013). "Clinically, a rise in MPO-ANCA titers during remission was often predictive of a future relapse in MPO-ANCA-associated vasculitis." (PMID 23504409, 2013). "In contrast, BN rats, that harbor high amounts of CD45RClow T cells, preferentially develop heavy metal-induced type-2 immune-mediated disorders and MPO-ANCA associated vasculitis." (PMID 19381293, 2009). "An animal model of ANCA associated vasculitis has been attempted by raising antibodies to MPO in MPO-/- knockout mice." (PMID 18625057, 2008). "Approximately 15 years after his initial EGPA diagnosis - and prior to receiving any immunotherapy - he developed progressive lower limb weakness and sensory symptoms, prompting the current admission and revealing a relapse of myeloperoxidase (MPO)-positive ANCA-associated vasculitis." (PMID 42037849, 2026). "Similarly, anti-proteinase 3 (PR3) and anti-myeloperoxidase (MPO) antibodies in individuals with ANCA-associated Vasculitis (AAV) also showed increased Fab glycosylation." (PMID 41301426, 2025). "In autoimmune disorders such as SLE, ANCA-associated vasculitis, RA, Gout, and psoriasis, defective NETs clearance and exposure of autoantigens like citrullinated histones, MPO, and PR3 contribute directly to loss of immune tolerance and sustained inflammation." (PMID 41335221, 2025). "ANCA-associated vasculitis is a heterogeneous group of rare diseases that present necrotising inflammation of small–medium vessels in conjunction with two major antigens targeted by ANCA for proteinase 3 (PR3) or myeloperoxidase (MPO)." (PMID 38337770, 2024). "Inadequate inhibition of MPO by low ceruloplasmin levels may contribute to a more severe phenotype in ANCA-associated vasculitis by enhancing oxidative stress and tissue damage through increased MPO activity and interaction with ANCA anti-MPO." (PMID 39388433, 2024). "ANCA directed against PR3 or MPO are well-known diagnostic markers for ANCA-associated vasculitis." (PMID 35243934, 2022). "Additionally, high expression levels of serum IFN-ɤ and TNF-α were observed in patients with myeloperoxidase-antineutrophil cytoplasmic antibody-associated vasculitis who were positive for anti-moesin auto-Ab." (PMID 34577564, 2021). "Release of proteinase 3 (PR3) and myeloperoxidase (MPO) may initiate antineutrophil cytoplasmic antibody-associated vasculitis." (PMID 34017259, 2021).